NOS2 (nitric oxide synthase 2)
Diseases named in the same sentence as NOS2 in open-access papers (continued):
Sharing a sentence is not in itself a finding about the gene and the disease.
asthma (continued). "Asthma data results show that NOS2 is resting with Mast cells (R = 0.26, p = 0.014), TIMP1 is resting with Plasma cells (R = 0.27, p = 0.011), CHI3L1 is resting with Neutrophils (R = 0.38, p = 0.00029) is positively correlated." (PMID 40443529, 2025). "Overall, these analyses show an involvement of DNA sensing pathway, weakening of the epithelial barrier and upregulation of pro‐inflammatory markers such as NOS2 after RV infection in patients with asthma." (PMID 39466641, 2025). "NOS2 has multiple roles in the airways, its expression being highest in severe asthma, while ARG1 decreases." (PMID 39466641, 2025). "NOS2 was significantly increased after infection in patients with asthma compared to the controls, while ARG1 was downregulated in patients with asthma." (PMID 39466641, 2025). "In conclusion, our bioinformatics analysis identified NOS2, TCN1, CHI3L1 and TIMP1 as potential diagnostic biomarkers for asthma and UC." (PMID 40443529, 2025). "In the mouse model of asthma consisting of NOS2 knockout mice, allergen challenge upregulated protein levels of ARG1 and ARG2 40-fold and 4-fold, respectively." (PMID 36061615, 2022). "NOS1-KO mice recruit fewer eosinophils (~ 70% of wild-type) and produce less NO (~ 10% of wild-type) in a mouse model of OVA-induced asthma, and upregulation of NOS2 is abolished." (PMID 29792217, 2018). "NOS2 mRNA expression is induced by pro-inflammatory cytokines, and is increased in asthma in proportion to the severity of the disease, and in particular by allergen provocation." (PMID 30240401, 2018). "Further, we discovered that the observed joint effects of short-term PM2.5 exposure, genetic and epigenetic variation in NOS2 are greater among children with asthma and children identifying as Hispanic white who already have high FeNO level." (PMID 28821285, 2017). "Although asthma prevalence rate in our study population are in line with national prevalence estimates, the study was not adequately powered to detect significant three-way interactive effects of asthma, NOS2 haplotype and road length measures." (PMID 26714306, 2015). "We evaluated the joint effects of asthma, NOS2 H1 promoter haplotype and length of local roads around home on FeNO in children." (PMID 26714306, 2015). "The third isoform, the inducible NOS (NOS2) is upregulated in airways inflammation (i.e., airway epithelial cells isolated from patients with asthma." (PMID 24727374, 2014). "In conclusion, this study identified NOS2 and NOS3 polymorphisms associated with higher levels of EBC NO2–NO3 and FeNO, and evidenced a modifying effect of asthma status on the associations between NOS3 genetic variants and FeNO levels." (PMID 22590587, 2012). "In addition, we identified NOS2, TCN1, CHI3L1, and TIMP1 as possible diagnostic markers for UC and asthma." (PMID 40443529, 2025). "The most increased protein in EVs released upon stimulation with T2 cytokines was NOS2 which has been shown to be upregulated in the respiratory epithelium of patients with asthma and is the main producer of exhaled nitric oxide, a biomarker of T2 asthma." (PMID 32560723, 2020). "Moreover, levels of FeNO were decresed in severe asthma current smokers, and was correlated with NOS2 mRNA expression in bronchial brushing." (PMID 30240401, 2018). "However, this is the first study in severe asthma showing a clear relationship between cigarette smoking and reduced NOS2 expression together with lower levels of FeNO." (PMID 30240401, 2018). "We infer that the observed larger associations of PM2.5, genetic and epigenetic variations in NOS2 among the children already having high FeNO level are not fully attributable to the presence of asthma." (PMID 28821285, 2017). "While children with asthma had significantly higher FeNO than those without asthma, there were no statistically significant three-way interactive effects of asthma, NOS2 H1 haplotype and road lengths within 100m and 200m buffers on FeNO (both P-values for interaction > 0.6)." (PMID 26714306, 2015).
asthma (continued). "In addition, result of epistatic analysis showed only significant epistatic effect between two variants within NOS2, suggesting that this combination affects asthma susceptibility, but not FeNO levels." (PMID 34946286, 2021). "Furthermore, MMP-12 has been suggested to regulate the expression of NOS2, which has been shown to be upregulated in the airway epithelium of patients with asthma and is the main producer of exhaled nitric oxide, which is a surrogate biomarker of eosinophilic airway inflammation." (PMID 33946872, 2021). "However, only four variants in NOS2 gene were investigated in that study, and the modifying effect of asthma was not studied." (PMID 22590587, 2012). "In children without asthma, significant associations have been evidenced between FeNO levels and genetic variants of NOS2 promoter region (including rs1889022 and rs10853181, two SNPs in LD with rs6505510 (D′ = 1, r2 = 0.4) associated with FeNO levels in adults without asthma in our study)." (PMID 22590587, 2012). "GSEA analysis showed that NOS2, TCN1, CHI3L1 and TIMP1 were jointly involved in cytokine receptor interaction in asthma and ulcerative colitis chemokine signaling pathway." (PMID 40443529, 2025). "Then, the genes selected by the two methods were crossed, and finally, the key genes involved in the progression of asthma to UC (CXCL13, NOS2, TCN1, CHI3L1 and TIMP1) were obtained." (PMID 40443529, 2025). "This study highlights NOS2, TCN1, CHI3L1, and TIMP1 as potential biomarkers and therapeutic targets for asthma and UC, providing insights into shared mechanisms and new strategies for diagnosis and treatment." (PMID 40443529, 2025). "In conclusion, NOS2, TCN1, CHI3L1 and TIMP1, as key immune and inflammatory regulatory targets, play an important role in the comorbidity of asthma and ulcerative colitis." (PMID 40443529, 2025). "The results showed that only four genes (NOS2, TCN1, CHI3L1, TIMP1) showed statistically significant differences in expression in the data sets validated by asthma and UC compared with the control group." (PMID 40443529, 2025). "Between moderate and mild asthma, KEGG analysis showed that the “HIF-1 signaling pathway” was the most significant signaling pathway, with TFRC, NOS2 and ERBB2enrichment." (PMID 38351296, 2024). "In this sense, the NFκB must participate in the pro-resolving pathways induced by CPC treatment because, in the OVA-induced asthma model, there is a similar pattern of COX2, NOS2, and MPO expression, as well as the reduction of proinflammatory cytokines." (PMID 39000141, 2024). "In BALB/c-OVA model of asthma, the HIF-1α antagonist YC-1 suppressed HIF-1α expression and lowered the transcript levels of IL-5, IL-13, myeloperoxidase, and NOS2." (PMID 35453294, 2022). "Nineteen differentially expressed PRGs were included in the mild-to-moderate and severe asthma samples, among which CAPN1, NLRP1, TRIM31, NOS2, and CDC37 showed the highest difference (P<0.01)." (PMID 35967302, 2022). "Quercetin, luteolin, linolenic acid, adenosine, kaempferol, etc., were considered the potential core compounds, and PTGS2, ESR1, PTGS1, NOS2, AKT1, etc. were the main potential targets of BSYQ for asthma and IPF therapy." (PMID 35672815, 2022). "For examples, significant DEGs in our list are involved biomarkers of Th2 response (POSTN), inflammation (NOS2, ALOX15) and mucus production (MUC5AC) corroborated with a previous metanalysis of airway gene expression in asthma." (PMID 32900903, 2020). "In children with asthma, DNA methylation of candidate genes (such as IL6 [IL-6] and NOS2 [inducible nitric oxide synthase]) in nasal epithelium is associated with exhaled nitric oxide (FeNO), a marker of airway eosinophilic inflammation." (PMID 31001502, 2019). "Many other pathways were also identified that are regulated by IL-13 and relevant to asthma pathogenesis (e.g. CCL17, CCL26, CTGF, FCER1A, KITLG, MUC2, NOS2, TLR3)." (PMID 29367592, 2018).
asthma (continued). "SNPs (N = 121) belonging to NOS1, NOS2 and NOS3 genes were genotyped in 1277 adults from the French Epidemiological study on the Genetics and Environment of Asthma (EGEA)." (PMID 22590587, 2012). "This list included many genes with a purported role in regulation of the immune response in asthma: interleukins (IL2IL27 and IL33), chemokines (CXCL1CXCL17CCL5 and CCL27), mucins (MUC2MUC13 and MUCL1), TLR7 and NOS2, among others." (PMID 22713245, 2012). "These specific genes, whose expression was attenuated by clarithromycin after IL-13 exposure, were dominantly categorized as “extracellular region,” “plasma membrane,” and “defense response” genes, among which asthma-related CD40, NOS2, and CXCL1 were included." (PMID 28219384, 2017).
breast carcinoma (52 papers, 2012 to 2026). "One of the most effective prognostic indicators for ER- breast cancer is the association between NOS2 and COX2." (PMID 37169743, 2023). "Nitric oxide synthase 2 (NOS2), a biomarker of early cancer development, cancer progression, and patient survival, has been implicated in breast cancer, brain metastases, and ovarian cancer." (PMID 37684587, 2023). "This analysis found that low NOS2 expression was associated with lowered metastasis in ER+ breast cancer patients that were treated with tamoxifen." (PMID 35740092, 2022). "Our finding is consistent with a previous study that reports the association with high NOS2 expression and metastasis in breast cancer patients." (PMID 29484119, 2018). "NOS2 expression is associated with a basal-like phenotype in ER- breast tumors and NO signaling results in increased expression of basal-like signature genes in ER- human breast cancer cell lines." (PMID 22971289, 2012). "The results indicated that high expression levels of OPN4, NOS2, GPR157, NCOA2, CLOCK, and TH were associated with shorter OS in breast cancer patients, while high expression of EGR3, NR1H3, RELB, SIAH2, and ADRB1 was linked to improved survival rates." (PMID 41031266, 2025). "The combination of low SerpinB2, high NOS2, and low CD206 expression was associated with good DFS in patients with breast cancer with LN metastasis (n = 272, HR = 0.5329, P = 0.0341)." (PMID 38956496, 2024). "Increased NOS2 expression correlates with poor survival across different tumors, including breast cancer." (PMID 38892290, 2024). "The BreastMark website was used to explore the association between SerpinB2, NOS2, and CD206 expression, and DFS in patients with breast cancer." (PMID 38956496, 2024). "Consistent with the protein levels, we observed substantially higher NOS2 mRNA expression in MpBC tumors compared to other breast cancer subtypes by performing quantitative PCR (qPCR) analysis in the corresponding 35 PDX models." (PMID 39737957, 2024). "Data extracted from the TCGA indicates a significant upregulation of NOS2 in ER- breast cancer patients compared to normal tissue, with a fold change of 13.9." (PMID 38892290, 2024). "In summary, this spatial arrangement suggests a significant association between NOS2 and COX2 niches that drive poor clinical outcomes in ER- breast cancer." (PMID 38892290, 2024). "We show that in PyMTSB2−/− mice, SerpinB2 deficiency delays mammary tumor initiation, growth, and LN metastasis, which is accompanied by a decrease in CD206+M2 TAMs and an increase in NOS2+M1 TAMs." (PMID 38956496, 2024). "In breast cancer, the co-expression of NOS2 and COX2 is involved in the regulation of oncogenic pathways such as ERK, PI3K and NF-κB results in a poor prognosis." (PMID 37346068, 2023). "More importantly, NOS2 has been proven to predict a poor prognosis in breast cancer, glioma, melanoma, pancreatic cancer, gastric cancer, liver cancer, and colon cancer." (PMID 37958916, 2023). "Based on cBioportal analysis, we found that the overall survival time of breast cancer patients with one gene mutation in PRKDC, NOS2, ARG1, or IDO1 was significantly shorter compared with patients without the mutations." (PMID 36373232, 2023). "For example, NOS2 inhibitors can assist photodynamic therapy to eradicate cancer cells in animal models of prostate cancer and breast cancer." (PMID 37795447, 2023). "This indicated that mutations in PRKDC, NOS2, ARG1, and IDO1 were correlated to lower overall survival in breast cancer patients." (PMID 36373232, 2023). "Along similar lines, inhibition of nitric oxide (NO) production by MDSCs with a nitric oxide synthase 2 (NOS2) inhibitor reportedly restores NK-cell mediated ADCC in preclinical models of breast cancer, resulting in superior tumor control in vivo." (PMID 36319998, 2022).
breast carcinoma (continued). "The gene-disease interaction network suggests the potential role of CXCL8, NOS2, and IL-6 in mediating mammary neoplasms, inflammation, hyperalgesia, cholestasis, and neoplastic cell transformation." (PMID 35720847, 2022). "In contrast, elevated levels of Trib1 in myeloid cells led to an increased late-stage mammary tumor volume, coupled with a reduction of NOS2 expressing macrophages and an overall reduction of macrophages in hypoxic tumor regions." (PMID 35664073, 2022). "The upregulation of miR-193b exerts antitumoral properties through reducing NOS2 activity in breast cancer (Figure 3A3)." (PMID 34200849, 2021). "NOS2/iNOS has been found to be upregulated in many cancers, including gastric cancer, breast cancer, CRC, pancreatic cancer, and prostate cancer." (PMID 34439295, 2021). "As a matter of fact, high levels of NOS2 have been found in metaplastic breast cancer, correlating with a poor clinical outcome." (PMID 34200849, 2021). "In breast cancer cells hypoxia-stabilized HIF1α upregulates the inflammatory protein NOS2 in conditions of nutrient deprivation, and NO promotes tumor cell survival, proliferation, and cell migration and mediates drug resistance." (PMID 33859337, 2021). "In breast cancer patients, L-Arg is depleted by nitric oxide synthase 2 (NOS2) and arginase 1 (ARG-1) produced by myeloid-derived suppressor cells (MDSCs)." (PMID 27246354, 2016). "Accordingly, both forced NOS2 over-expression and exposure to NO-donors resulted in significant Ets-1 transcriptional activation in ER- breast cancer cells." (PMID 22971289, 2012). "Because NOS2 expression resulted in Ets-1 (thr 38) phosphorylation, we also examined the effect of NO signaling on Ets-1 activation in human ER- breast cancer cell lines treated with NO releasing compounds." (PMID 22971289, 2012). "Furthermore, Prueitt and colleagues analyzed NOS2 expression in a cohort of 248 breast cancer patients and reported that 29% and 41% of the patients exhibited moderate and high NOS2 expression, respectively." (PMID 38892290, 2024). "Besides, the overall survival time of breast cancer patients with at least one gene mutation in PRKDC, NOS2, ARG1, and IDO1 (1191 patients) was significantly shorter compared with patients without the mutations (4575 patients)." (PMID 36373232, 2023). "In breast cancer, increased NOS2 has been reported in >70% of patients." (PMID 37169743, 2023). "Moreover, EMT is finely tuned by M-MDSC-mediated nitric oxide synthase (iNOS; also known as NOS2) in breast cancer." (PMID 34576042, 2021). "Skeletal muscle Nos2 expression in PyMT+ mammary tumor mice compared to wild type mice was significantly lower, which may have an impact on recovery from injury." (PMID 31941005, 2020). "The breast cancer cell line BT474 is used as a robustly positive control for NOS2 RNA." (PMID 23509693, 2013). "Together, these results suggest that the effects of aberrantly high TIMP-1 and NOS2 on breast cancer outcome may be mechanistically interrelated." (PMID 22957045, 2012). "Recently, we reported that high NOS2 expression is a predictor of poor patient outcome in estrogen receptor-negative (ER-) breast cancer and is functionally linked to the development of a basal-like breast cancer phenotype." (PMID 22971289, 2012). "Our study made the novel observation that the oncogenic transcription factor Ets-1 is a critical mediator of NOS2 and NO-induced signaling in breast cancer and thus, this study provides a molecular mechanism that at least partly explains the oncogenic effects of NO in ER- breast cancer." (PMID 22971289, 2012). "Furthermore, overexpression of NOS2 and experimental exposure to NO resulted in Ets-1 (threonine 38) phosphorylation and increased transcriptional activity in ER- breast cancer cell lines." (PMID 22971289, 2012). "Thus, we examined the role of NOS2 activity and NO signaling in the activation of the Ets-1 transcription factor in human ER- breast cancer cell lines." (PMID 22971289, 2012).